NACAD (NAC alpha domain containing)
Description:
May prevent inappropriate targeting of non-secretory polypeptides to the endoplasmic reticulum (ER). May bind to nascent polypeptide chains as they emerge from the ribosome and block their interaction with the signal recognition particle (SRP), which normally targets nascent secretory peptides to the ER. May also reduce the inherent affinity of ribosomes for protein translocation sites in the ER membrane (M sites) (By similarity).
Synonyms: KIAA0363
Tractability: PROTAC: ubiquitination databases record sites on it; its protein half-life has been measured.
Gene: Protein-coding gene on chromosome 7 (45,080,437 to 45,088,969, reverse strand). Ensembl gene ENSG00000136274.
Subcellular location: Cytoplasm; Nucleus
Subcellular location (Human Protein Atlas): Cytosol; Nucleoplasm
Gene Ontology:
Molecular function: protein binding
Biological process: protein targeting to membrane
Cellular component: cytoplasm; nascent polypeptide-associated complex; nucleus
Genetic constraint (gnomAD): Loss-of-function variants: 47 observed, 91.67 expected, observed/expected ratio (o/e) 0.51, 90% interval 0.41 to 0.65. The upper end of that interval is the gene's LOEUF score, 0.65, which puts it in group 2 of 6, group 1 being the genes least tolerant of losing a copy. Missense variants: 1,388 observed, 1,639.3 expected, observed/expected ratio (o/e) 0.85, 90% interval 0.81 to 0.88. Synonymous variants: 680 observed, 717.49 expected, observed/expected ratio (o/e) 0.95, 90% interval 0.89 to 1.01.
Homologues: Orthologues: chimpanzee NACAD (93% identical), macaque NACAD (92% identical), rat Nacad (58% identical), mouse Nacad (54% identical), rabbit NACAD (51% identical), dog NACAD (45% identical), zebrafish nacad (22% identical), tropical clawed frog nacad (22% identical), Drosophila melanogaster Nacalpha (7% identical). Paralogues in human: NACA (17% identical), NACA2 (8% identical).
Diseases named in the same sentence as NACAD in open-access papers:
NACAD is named in the same sentence as 2 diseases in open-access papers, as found by Europe PMC text mining. Sharing a sentence is not in itself a finding about the gene and the disease. The quoted sentences say what the papers report.
breast carcinoma (2 papers, 2023 to 2024). "Kaplan-Meier curves show that SDC1, NACAD, ZMAT3, CCND2, XG and SGCE are associated with prognosis in breast cancer patients." (PMID 39664194, 2024).
dermatomyositis (1 paper, 2026). Dermatomyositis (DM) is a type of idiopathic inflammatory myopathy characterized by evocative skin lesions and symmetrical proximal muscle weakness. "Using LASSO regression, SVM, random forest (RF), GBM, GLM, KNN, and NNET machine learning algorithms, four core genes were identified: SAA1, NACAD, SLC14A1, and MYBPH, all of which were highly expressed in dermatomyositis lesion tissues." (PMID 41911226, 2026).